CD4 (CD4 molecule)
Diseases named in the same sentence as CD4 in open-access papers (continued):
Sharing a sentence is not in itself a finding about the gene and the disease.
infection (continued). "It is therefore still unclear to what degree activation status influences infection-induced networked cell death, and further examination of the susceptibility of particular subsets of T cells, such as CD4+ or CD8+, would also be of utility." (PMID 22675566, 2012). "Our findings suggest that CB2R activation in CD4+ T cells can inhibit actin reorganization and impair productive infection following cell-free or cell-associated viral acquisition of CXCR4-tropic HIV-1 in resting cells." (PMID 22448282, 2012). "We found that all the HIV-1 variants were capable of transmitting infection to cervical tissue ex vivo and in this system preferentially replicate in activated CD4 T cells and deplete these cells." (PMID 23236398, 2012). "It has been postulated that in patients infected with HIV, the risk of postoperative infection is increased due to the decline in the number of CD4 cells." (PMID 22905120, 2012). "When gp120 has access to bind α4β7, there exists a capacity for a population of CD4+ T cells to be highly susceptible to infection with HIV-1." (PMID 22731404, 2012). "Multivariable logistic regression showed that TDR was positively associated with men who have sex with men (MSM) and subtype B infection and negatively associated with CD4 cell counts." (PMID 22448246, 2012). "The most common amongst these pathogens were the opportunistic gastrointestinal parasites, C. parvum, and I. belli which cause infection when there is a downregulation of the immune system as is seen with decreasing CD4 levels." (PMID 23326669, 2012). "Among animals with favorable MHC alleles, the restrictive TRIM5 genotypes were strongly associated with protection from infection, while for the other macaques NAbs and Env-specific CD4+ T-cells were the best correlates." (PMID 23025660, 2012). "Unsurprisingly, inappropriate T cell activation is associated with increased susceptibility of CD4 T cells to infection and decreased T cell responsiveness to antigenic stimulation, including reduced IL-2 production, and increased apoptosis." (PMID 22958464, 2012). "It is known that this retrovirus preferentially infects activated CD4+ T cells, but infection rates are very low even in this susceptible population." (PMID 22876188, 2012). "Recent studies in HIV-infected individuals and simian models of infection demonstrated that depletion of CD4+ T-cells from gut-associated lymphoid tissues (GALT) occurs very early upon infection." (PMID 22470433, 2012). "This trend has been described for CD4 T cells generated by protein vaccines compared with infections, and likely reflects the influence of infection-associated innate signals and the induction of factors that drive Th1 polarization." (PMID 22457834, 2012). "Here we demonstrate that during direct infection of resting CD4+ T cells, HIV-1 is capable of causing activation and proliferation of resting CD4+ T cells in vitro, while deletion of Nef and mutations within Nef can reduce this effect." (PMID 22479639, 2012). "CD4+ cells, numbers of which significantly increase in the skin after challenge infections, are potential sources of IL-4 associated with Th2 response." (PMID 23125918, 2012). "An allogeneic system was used to assess the ability of lung CD11c+ cells derived from all infection groups to imprint mucosal associated TRs on CD4+ cells." (PMID 23300813, 2012). "While HIV directly and selectively infects CD4+ T cells, the low levels of infected cells in patients is discordant with the rate of CD4+ T cell decline and argues against the role of direct infection in CD4 loss." (PMID 23202514, 2012). "LP-BM5 infection caused significant increase in B220 and CD4 expressing cells in mA3-dependent manner." (PMID 22691411, 2012).
infection (continued). "Humanized mice provide a simple model to study HIV pathogenesis without the need for more expensive systems like SHIV or SIV infection of rhesus macaques while providing fairly similar pathology to human infections in terms of virus replication and CD4 loss." (PMID 23202514, 2012). "Decreased fungal burdens and Foxp3+ Treg cells (CD4+CD25+Foxp3+), which were associated with increased numbers of effector CD4 T (CD44highCD62low) cells, were detected at week 2 post-infection." (PMID 23226464, 2012). "TMEV-infection in susceptible strains of mice induces chronic demyelinating disease that is primarily mediated by CD4+ T cells." (PMID 22985464, 2012). "In the present study, we sought to evaluate the impact of breast milk on infection of CD4+ target cells by cell-free and cell-associated HIV-1 in vitro." (PMID 22952771, 2012). "In previous analysis of HIV-1 superinfection (SI), infection with a second virus during the course of an established infection was generally associated with loss of viral control and abrupt decline in CD4+ T cells counts." (PMID 22384103, 2012). "Decreased fungal burdens and Treg cells (CD4+ Foxp3GFP), which were associated with increased numbers of effector CD4+ T (CD44highCD62low) cells, were detected at week 2 post-infection." (PMID 23226464, 2012). "We analyzed the association of BSSL genotype with set-point viral load and CD4 cell count, both pre-infection and post-infection at viral set-point." (PMID 22412885, 2012). "Further, multiple infections generated an IL-17+ IFN-γ+ double positive population of CD4+ T cells that are known to be associated with autoimmune disease in humans and directly responsible for autoimmune pathology in rodent models." (PMID 21966268, 2011). "While recruiting HIV-susceptible CD4+ T cells to the site of infection, cytokines/chemokines also lead to increased recruitment of HIV-specific CD8+ T cells." (PMID 21858117, 2011). "Direct routes of infection (intraperitoneal or intravenous) give similar results for CD4+ T cell loss, while limited data on mucosal transmission indicate that slower and less severe loss occurs." (PMID 21835012, 2011). "Only weight loss was significantly associated with infection (OR = 3.1; 95% CI: 1.4–7.2) when controlling for CD4+ cell count and VL." (PMID 21532747, 2011). "To assess immune responses during vaccination and infection, we measured antigen-specific antibody isotype titres as a surrogate of the underlying CD4+ T cell response, given the known correlation between IL-4 and IgG1 responses and between IFNγ and IgG2a." (PMID 22216363, 2011). "HIV infection is associated with a progressive decline of circulating CD4+ T cells and loss of immune functions; however this infection shows a more severe depletion of CD4+ T cells in the gastro-intestinal tract than in blood." (PMID 21994747, 2011). "CXCR4-tropic SHIV89.6P infection causes an accelerated disease progress with rapid systemic loss of all CD4+ T cell phenotypes compared to CCR5-tropic SIV and HIV." (PMID 21359149, 2011). "Our initial prediction was that CD4+ cell recovery by BAL would rapidly increase as infection-induced inflammation caused the recruitment of secondary effector cells." (PMID 21647373, 2011). "HIV infection leads to a disproportionate loss of CD4+ T cells, which in experimental models have been shown to be essential for controlling infection with BCG." (PMID 21264335, 2011). "A biphasic destruction of CD4+ T cells is observed in HIV infection with a massive loss of CD4+ T cells during early infection and a subsequent progressive loss during the chronic stage of infection." (PMID 21752277, 2011). "When normalized by the titer of VSV vector, susceptibility of TE671 cells to the CD4-independent mNDK vector infection was about 60% of that in 293T cells." (PMID 21541353, 2011).
infection (continued). "We show here that CD4+ T cells from Patient 169 are fully susceptible to infection and that he had very low titers of neutralizing antibodies to heterologous and autologous virus." (PMID 22141397, 2011). "CD4+ T cells from 169 were as susceptible to infection with both types of isolates as were the CD4+ T cells from the seronegative donors." (PMID 22141397, 2011). "Specifically, the affinity of gp120 for α4β7 provides a mechanism for HIV-1 to target a subset of CD4+ T cells that are highly susceptible to infection." (PMID 21284901, 2011). "The presence of gp120 in LN of RM during early infection was shown to be associated with dysregulated IFN-γ responses of CD4 and CD8 T cells." (PMID 21483689, 2011). "The underlying mechanisms for the accelerated loss of the naïve CD4+ T-cells during HIV-1 disease most likely include increased recruitment into the effector/memory pool as well as direct infection with HIV-1 and eventual cell death." (PMID 21298072, 2011). "IL-6-deficient mice that survived infection became long-term carriers despite the presence of abundant IFN-γ-producing 2W:I-Ab-specific CD4+ T cells." (PMID 21966268, 2011). "In subtype B infected subjects, baseline infection with a CXCR4-using virus is strongly associated with a greater decrease in CD4+ T cell count over time and a greater risk of disease progression." (PMID 21969855, 2011). "Acute SIVagm infection of RMs was similar to pathogenic infection, being characterized by robust acute viral replication and massive mucosal CD4+ T cell depletion." (PMID 21829366, 2011). "In agreement with the data presented here, infection of MyD88-deficient mice with Mycobacterium bovis BCG also triggered CD4+ T-cells to produce IFNγ." (PMID 22096480, 2011). "During the chronic phase, peripheral CD4+ T counts rebounded to preinfection levels starting from day 200 p.i. on, in contrast to pathogenic infections." (PMID 21829366, 2011). "Intracellular CD4+-ATP-concentration (iATP) functionally reflects cellular immunocompetence and inversely correlates with risk of infections during immunosuppressive therapy." (PMID 21533133, 2011). "Studies of the infection of Chinese rhesus macaques with pathogenic SIV have also reported that peak plasma SIV RNA loads were associated with the loss of intestinal CD4+CCR5+ T cells." (PMID 21291552, 2011). "In association, previous studies have shown the importance of IFNγ-producing CD4+ T-cells in increasing resistance of RAG-1/IFNγ-double-deficient mice against an infection with C. pneumoniae." (PMID 22096480, 2011). "This corresponded with peak viremia and depletion of total CD4+ T cells as a result of pathogenic FIV infection." (PMID 21364928, 2011). "Conversely CD4+ T cell specific (LckcreIL-4Rα−/lox) IL-4Rα−/− mice are more susceptible than global IL-4Rα−/− mice to infection with L. mexicana, indicating a role for an IL-4/IL-13 responsive non CD4+ T cell population in early susceptibility." (PMID 21245915, 2011). "WNV-specific IgM levels decreased about 20-fold at day 15 post-infection in CD4-deficient mice and IgG levels were about 100- to 1,000-fold lower throughout the course of infection compared to wild-type mice." (PMID 21994755, 2011). "Enhanced IFNγ-responses by C. pneumoniae-specific CD4+ T-cells in TLR2/4 double-deficient mice are best explained by an impaired infection-associated expansion of CD4+CD25+Foxp3+ regulatory T-cells." (PMID 22096480, 2011). "This component has been termed transitory infection and is presumably sustained by infected and susceptible CD4+ T cells trafficking into the meninges and brain." (PMID 21569420, 2011). "In the case of a chronic nasal carriage, the risk for SA infection rose to 20% per year among patients with CD4+ <100 cell/mm3." (PMID 22022439, 2011). "All four independent hybridoma cell pools were as susceptible to the CD4-independent mNDK vector infection as 293T cells." (PMID 21541353, 2011).
infection (continued). "Infection results in acquired immunodeficiency syndrome associated with progressive loss of CD4+ T-lymphocytes." (PMID 21887365, 2011). "The association between sCD4 sensitivity, sgp120 CD4-Ig binding and infection of CD4low cells was also seen for R5 viruses evolving following the time of coreceptor switch at 20 wpi in BR24." (PMID 21760891, 2011). "Statistical analysis reveals that susceptibility to the CD4-independent mNDK vector infection was reverse-correlated with cathepsin B activity of the target cells." (PMID 21541353, 2011). "In a repeat of the study in a larger set of mice consisting of 6 mice per group the results were identical, confirming the differential loss of CD4 cells in WT versus V38E infections." (PMID 21255440, 2011). "Infection with the domestic cat (Felis catus) strain of FIV (FIVFca) results in CD4+ T-cell depletion and pathogenic disease which progresses to AIDS-like immune dysfunction and ultimately death." (PMID 22069521, 2011). "CD4 levels on macrophages are quite low, and greater macrophage infection capacity among R5 strains has been linked to the ability to utilize CD4 at very low levels." (PMID 21284902, 2011). "Infection with PLV protects cats from CD4+ T-cell decline caused by subsequent infection with virulent feline immunodeficiency virus (FIV)." (PMID 22069521, 2011). "Accordingly, in the small intestine, where the majority of mucosal T cells express CCR5, infection with CCR5-tropic HIV-1 causes massive depletion of CD4 T cells." (PMID 21284905, 2011). "Cathepsin B activity was inversely correlated with cellular susceptibility to the CD4-independent HIV-1 vector infection." (PMID 21541353, 2011). "C33A cells were as susceptible to the CD4-independent mNDK vector infection as TE671 cells, and have similar level of cathepsin B activity to TE671 cells." (PMID 21541353, 2011). "Normalization by the titer of VSV vector indicated that the susceptibility of HeLa cells to the CD4-independent mNDK vector infection was only about 4% of that in 293T cells." (PMID 21541353, 2011). "Human Immunodeficiency Virus type-1 (HIV-1), the cause of the global AIDS pandemic, primarily infects CD4+ T lymphocytes and efficient replication necessitates transmission of infection to susceptible neighbouring cells." (PMID 21909273, 2011). "Peak viremia typically occurs in the range of 1-2 months post-infection; however, CD4+ T cell loss in the blood is more severe with CXCR4 virus and the decrease in target cells is accompanied by a decrease in viremia." (PMID 21835012, 2011). "As have been demonstrated by several studies a selective and massive loss of infected CD4+ memory T cells occurs during the acute phase of infection." (PMID 22043290, 2011). "A growing body of work has also implicated CXCR4 and various chemokines in regulating infection of resting CD4+ T cells, an important latent reservoir of HIV in infected individuals." (PMID 21949786, 2011). "The ability of T cell-based vaccine candidates to induce protective immunity against infection has largely been associated with the capacity of antigen-specific CD4+ and CD8+ T cells to produce multiple effector functions simultaneously." (PMID 20478058, 2010). "In the SIV/macaque model, the earliest detectable targets of infection during vaginal transmission appear to be resting CD4 T cells in the lamina propria underlying the genital mucosa." (PMID 21994702, 2010). "At CD4 levels above 400, patients are at risk of infection from relatively virulent organisms, such as bacteria and TB." (PMID 20981180, 2010). "All cell lines were susceptible to infection, but Raji/CD4 cells gave the highest levels of Luc activity." (PMID 20195464, 2010). "Usually X4 and dual-tropic virus isolates appear later in the course of infection, and their appearance is usually associated with a faster decrease in CD4+ T cells count and the progression towards symptomatic disease." (PMID 21994649, 2010).
infection (continued). "Upon infection of C3-deficient mice with influenza virus, a significant impairment in priming of CD4+ helper cells and virus-specific cytotoxic T lymphocytes was observed, which resulted in delayed clearance of the infection and increased viral titers." (PMID 20442876, 2010). "The acute phase of HIV infection is characterised by extensive and rapid loss of CD4+ cells due to apoptosis that persists into the chronic phase of infection." (PMID 20109174, 2010). "In particular, subtype D infection was associated with both a statistically significant four-fold faster rate of CD4 decline and a higher rate of virological rebound on ART compared with subtype B and the other main non-B subtypes, A and C." (PMID 20205896, 2010). "We conclude that replication fitness evolves with pathogenicity and that variants that replicate most efficiently in CD4+ T cells are likely to dominate after subsequent infections." (PMID 20942954, 2010). "Taken together, Ye stimulates increased proliferation of DCs, but higher cell death rates combined with inhibition of de novo generation lead to loss of CD4+ and CD8α+ DC subsets upon infection." (PMID 21124820, 2010). "The reduction of the number of CD4+ T cells was also associated with a concern of possible increased susceptibility to infection." (PMID 20479941, 2010). "The effect of improved viral control in early infection in vaccinated animals can be seen as the decrease in the peak plasma viral load and reduced loss of CD4+ T cells in peripheral blood." (PMID 21152101, 2010). "Our data describing the development of sub-optimal humoral immunity following de novo γHV68 infection of aged mice is consistent with an age-associated CD4 T cell defect." (PMID 20181071, 2010). "CD4+T cells serve as both essential regulators and effectors of the immune response; infection with HIV induces a progressive loss of these cells." (PMID 20169116, 2010). "We have previously reported that a delayed recovery of CD4+ T-cell counts predisposes to a subsequent infection." (PMID 20090932, 2010). "The CD4+ T cell loss observed during the chronic phase of infection was initially thought to result from the death of productively infected CD4+ T cells, due to the cytopathic effects of viral replication and cytotoxic CD8-mediated killing." (PMID 20617170, 2010). "A more significant association between clustering and higher CD4 counts (p = 0.002) however, supports the relation between clustering and earlier infection stage." (PMID 20822507, 2010). "During chronic infection, it is well recognized that there is a loss of CD8+ and CD4+ reactivity in the blood towards a range of peptides, compared with patients where infection has been resolved." (PMID 20107020, 2010). "Because there is a well-established age-associated decline in CD4 T cell function, we examined the ability of aged naïve mice to control de novo infection as another measure of the impact of ageing on functional γHV68-specific immunity." (PMID 20181071, 2010). "The dependence of virus activation and inactivation on SCM concentration was particularly evident in the biphasic dose-effect curves associated with HIV-1(YU2) infection of CD4− CCR5+ target cells." (PMID 19343205, 2009). "Most simulation models assumed a fixed increase in risk of clinical progression per unit CD4 decline during untreated infection, throughout the spectrum of CD4 levels and infection stages." (PMID 19536329, 2009). "Infections with both human and feline immunodeficiency viruses cause progressive deterioration of immune responses and are characterized by decline of CD4 cells." (PMID 19806226, 2009). "The largest Phase IIa trial of RTS,S confirmed the strong association between anti-CS IgG titre and protection against infection and demonstrated an independent, albeit weaker, association between CS- specific CD4+ T cell responses and protection." (PMID 20042088, 2009).